BRCA1 (BRCA1 DNA repair associated)
Diseases named in the same sentence as BRCA1 in open-access papers (continued):
Sharing a sentence is not in itself a finding about the gene and the disease.
ovarian carcinoma (continued). "Likelihood ratios (LR) were calculated for the association of ovarian cancer histology and other characteristics, with BRCA1 and BRCA2 variant pathogenicity." (PMID 37076566, 2023). "In England, national guidelines specify that all women with newly diagnosed high-grade ovarian cancer undergo tumour testing for BRCA1/2 pathogenic/likely pathogenic variants and homologous recombination deficiency (HRD)." (PMID 36765687, 2023). "After ovarian cancer had been diagnosed, the patient was found to have a germline mutation of breast cancer susceptibility gene 1 (BRCA1)." (PMID 36911580, 2023). "Carrying germline pathogenic variants in BRCA1 or BRCA2 (gBRCA) confer a high risk for developing breast or ovarian cancer throughout a patient’s life." (PMID 37119509, 2023). "For tubal/ovarian cancer, the cumulative lifetime risk up to age 80 is 44% for BRCA1 GPV (95% CI: 36–53%) and 17% for BRCA2 GPV (95% CI: 11–25%)." (PMID 37046756, 2023). "This reduces the risk of tubal/ovarian cancer by >96% if performed before the incidence rises (recommended age range: 35–40 years for BRCA1 and 40–45 years for BRCA2)." (PMID 37046756, 2023). "In this study, ovarian cancer histological subtypes were evaluated as predictors of BRCA1 and BRCA2 pathogenic variant status." (PMID 37076566, 2023). "Risk factors for ovarian cancer include early first menstruation, late menopause, BRCA1 and BRCA2 gene mutations, obesity and asbestos and talc exposure." (PMID 37446063, 2023). "Our findings suggested that, in addition to breast and ovarian cancer, P/LP variants of BRCA1 also conferred increased risk for lung cancer in Chinese people." (PMID 37930190, 2023). "For BRCA1/2 pathogenic variant carriers, the risk of ovarian cancer, which is known for its very poor prognosis, is high." (PMID 36849964, 2023). "Genetic testing for hereditary breast and ovarian cancer revealed two pathogenic variants in the BRCA1 (c.5095C>T, p.(Arg1699Trp)) and in BRCA2 genes (c.658_659delGT, p.(Val220Ilefs*4)) in heterozygous form." (PMID 37895014, 2023). "We established an in vitro model for PARPi-resistant ovarian cancer by long-term olaparib exposure of either BRCA1-proficient or BRCA1-deficient cell lines." (PMID 37568590, 2023). "While secondary constitutional methylation of BRCA1 has been observed in a few families with an elevated risk of breast and ovarian cancer, the question of primary constitutional methylation as a cancer risk factor has remained controversial." (PMID 38053165, 2023). "As an additional treatment option, the inclusion of olaparib maintenance therapy demonstrated a significant advantage in terms of progression-free survival for women who were diagnosed with newly advanced ovarian cancer and carried a BRCA1/2 mutation." (PMID 37781206, 2023). "A case study conducted in women of Ashkenazi Jewish ethnicity with inherited mutations for BRCA1 showed that 54% of women who had BRCA1 mutations had a lifetime risk for developing ovarian cancer." (PMID 37110218, 2023). "Using a BRCA1-deficient ovarian cancer mouse model, PARPi was shown to increase the therapeutic effects of CTLA-4 blockade which, as a single therapy, had limited benefit." (PMID 36831435, 2023). "A meta‐analysis showed that the F allele of the F352 V polymorphism in Klotho gene protects against breast and ovarian cancer susceptibility and is associated with an overall risk of cancer in BRCA1 mutation carriers." (PMID 35841322, 2023). "Following a diagnosis of epithelial ovarian cancer, patients are routinely tested for germline and/or somatic (tumour) BRCA1/2 mutations." (PMID 38201604, 2023). "Melphalan efficiently targeted the DNA repair mechanisms in ovarian cancer patients with BRCA1/2 mutations." (PMID 37110218, 2023).
ovarian carcinoma (continued). "Recently approved PARP1 inhibitors for BRCA1/2-linked ovarian cancer (OC) produced major response rates for patients with BRCA1/2-linked advanced OCs." (PMID 37095508, 2023). "Melphalan was identified as a promising therapeutic agent for the treatment of ovarian cancer patients who harbored BRCA1/2 mutations." (PMID 37110218, 2023). "BRCA1/2 germline mutation is the strongest known genetic risk factor for epithelial ovarian cancer and are found in 6–15% of women with epithelial ovarian cancer." (PMID 36611214, 2023). "BRCA1 is a tumor suppressor gene that can increase predisposition to tumorigenesis after mutation, and this is mainly reflected in breast and ovarian cancer." (PMID 37114130, 2023). "Germline BRCA1/2 mutations are present in approximately 5% of all breast patients and 15% of all ovarian cancer patients." (PMID 37664050, 2023). "PARP inhibitors exploit the fundamental weakness of ovarian cancers with HR repair defects and show promising antitumor effects in ovarian cancers with BRCA1/2 mutations." (PMID 37206208, 2023). "Prior to the era of PARPi, index cases of ovarian cancer were selected for germline BRCA1/2 testing based on their risk of hereditary cancer, with age at diagnosis and family history used to determine risk." (PMID 36765687, 2023). "The lifetime risk of developing ovarian cancer (OC) is 39–44% for BRCA1 and up to 11–17% for BRCA2-mutated women, with an onset 5–10 years later." (PMID 36837501, 2023). "Meanwhile, about 20% of ovarian cancers are thought to be hereditary, and almost 32% are supposed to be caused by pathogenic mutations in the BRCA1 and BRCA2 genes." (PMID 36835955, 2023). "Contradictory to this finding, a small single-center study (n = 41) found a higher VAF of somatic BRCA1/2 mutations to be associated with longer PFS in ovarian cancer patients." (PMID 37400502, 2023). "As for ovarian cancer, the estimated penetrance by age 70 was 48.3% (95% CI = 38.8% to 57.9%) for BRCA1 mutation carriers and 20.0% (95% CI = 13.3% to 29.0%) for BRCA2 mutation carriers." (PMID 37781206, 2023). "The mutations of BRCA1/2 genes were mostly nonsense substitutions that had been mainly associated with breast and ovarian cancer with few exceptions." (PMID 38188288, 2023). "Some miRNAs have been used to stratify risk in patients with breast/ovarian cancer and are associated with BRCA1/2 mutations." (PMID 36831687, 2023). "The American Society of Clinical Oncology (ASCO) recommends germline genetic testing for BRCA1/2 and ‘other ovarian cancer susceptibility genes’ for all women diagnosed with EOC." (PMID 36805919, 2023). "Relative to the general population, carriers of mutant BRCA1/2 have a significantly high risk of both breast and ovarian cancer." (PMID 38136334, 2023). "•ASCO guidelines conclude that all women with epithelial ovarian cancer should have germline genetic testing for BRCA1/2 and other ovarian cancer susceptibility genes." (PMID 37181681, 2023). "BRCA1 is another major tumor suppressor gene that is reported to mutate in ovarian cancer and was determined to regulate glycolysis." (PMID 37110218, 2023). "Ovarian cancer risk factors include a family history of the disease; mutations in BRCA1/BRCA2 genes; early menarche; being nulliparous; the presence of endometriosis; a history of breast, uterine, or colorectal cancer; and late menopause." (PMID 38201468, 2023). "For ovarian cancer (OC), the risk is around 40–50% for BRCA1 and 15–30% for BRCA2 mutation carriers." (PMID 38203374, 2023). "Patients with ovarian cancer tended to have higher frequencies of BRCA1 and BRCA2 mutations, and the frequency of germline BRCA1 mutations (18/24, 75.00%) was higher than that of BRCA2 (11/19, 57.89%)." (PMID 37064128, 2023). "Women with BRCA1 and BRCA2 (BRCA1/2) pathogenic/likely pathogenic (P/LP) variants have a higher risk to develop breast and ovarian cancer." (PMID 36971799, 2023).
ovarian carcinoma (continued). "When another tumor-suppressor gene BRCA1 is mutated in the germ-line cells of the hereditary breast and ovarian cancer family, the RB protein is also phosphorylated and inactivated." (PMID 37743524, 2023). "Hereditary risk for the development of breast or ovarian cancer, due to BRCA1 or 2 mutations, along with the respective prophylactic measures, require further investigation, in order to improve the understanding of best clinical practices." (PMID 36826146, 2023). "The Manchester score is based on family history and pathological characteristics of the tumor and indicative of the risk of a germline BRCA1 or BRCA2 mutation for patients with breast or ovarian cancer." (PMID 36112334, 2023). "PARP inhibitors have been successfully used in patients with breast or ovarian cancer who carry BRCA1/2 germline mutations." (PMID 37566130, 2023). "About 5–10% of all ovarian cancer cases show familial clustering, and some 15–25% of familial ovarian cancer cases are mediated by high-penetrance mutations in the BRCA1 and BRCA2 genes." (PMID 37013556, 2023). "In 2016, the FDA authorized Rucaparib to treat advanced ovarian cancer cases with somatic BRCA1/2 or germline mutations." (PMID 37351512, 2023). "In BRCA1 mutation carriers, oral contraception lowered the risk of ovarian cancer by 45–50%, and in BRCA2 mutation carriers, it decreased the risk by 60%." (PMID 36835955, 2023). "BRIP1 mutations are associated with breast and ovarian cancers and encode a protein that interacts with BRCA1 and is involved in double-stranded DNA break repair." (PMID 36980802, 2023). "This aligns well with evidence indicating higher expression of this molecule in BRCA1-deficient tumours from breast and ovarian cancer patients." (PMID 38017453, 2023). "Women with a pathogenic or likely pathogenic variant (PV) in BRCA1 or BRCA2 have high lifetime risks of developing ovarian cancer." (PMID 37602539, 2023). "For carriers of BRCA1 mutations, the risk of developing breast and ovarian cancer by age of 80 years is estimated to be 72% and 44% respectively, while it is 69% and 17% respectively for BRCA2 carriers." (PMID 38274092, 2023). "This trial eventually led to the approval of olaparib for BRCA1/2-mutated ovarian cancer patients with at least two lines of previous chemotherapy." (PMID 37035242, 2023). "The cumulative lifetime risk of ovarian cancer is 16–68% and 11–30% in female BRCA1 and BRCA2 gene alteration carriers, respectively." (PMID 37917945, 2023). "The U.S. Food and Drug Administration has already limited the indication for PARP maintenance therapy for recurrent ovarian cancer to BRCA1/2 mutation-positive cases, and we believe that it is important." (PMID 37488223, 2023). "Women who are found to carry a BRCA1/2 pathogenic variant experience psychological distress due to an increased risk of breast and ovarian cancer." (PMID 36767056, 2023). "Olaparib was recently approved for first-line maintenance treatment in BRCA1/2-mutated, newly diagnosed, advanced ovarian cancer after a complete response (CR)/partial response (PR) to platinum-based chemotherapy." (PMID 36829496, 2023). "On the other hand, a previous research demonstrated a higher prevalence of BRCA2 mutations compared to BRCA1 in other cancer types, including populations at increased risk for hereditary breast and ovarian cancer." (PMID 37804357, 2023). "Pathogenic variants in BRCA1/2 are also associated with ovarian cancer risk, as are pathogenic variants in PALB2, RAD51C, and RAD51D." (PMID 36765408, 2023). "Several mutations in the BRCA1/BRCA2 genes are known to increase the risk of developing ovarian cancer." (PMID 36981032, 2023). "Our five patient‐derived HRDhigh MFS and UPS cell models show sensitivity to both PARPi, with IC50 in a comparable range as the IC50 in BRCA1‐mutated ovarian carcinoma cells." (PMID 36779660, 2023).
ovarian carcinoma (continued). "In the clinical routine, patients undergo BRCA1/2 mutation testing if they show family breast or ovarian cancer history." (PMID 37568663, 2023). "PARP1 inhibitors, in particular Olaparib, are currently used in the clinic to treat breast and ovarian cancer patients carrying germline mutations in BRCA1/235." (PMID 36707518, 2023). "Mutations in the BRCA1/2 genes that result in dysfunctional HR incur a high risk of breast and ovarian cancer development." (PMID 37066268, 2023). "As a result, managing the risk of ovarian cancer is critical for women who have a PV in BRCA1 or BRCA2." (PMID 37602539, 2023). "Compared to BRCA1/2-deficient ovarian cancer tumors, the GIS distribution was significantly different for BRCA1/2-deficient ER + BC tumors, but not TNBC tumors." (PMID 37589839, 2023). "BRCA1, for which germline carriers of pathogenic variants face significant lifetime hereditary breast and ovarian cancer risks, frequently presents as a VUS in individual sequencing results." (PMID 37917606, 2023). "MiR-146a, miR-148a, and miR-545 are linked to improved outcomes in ovarian cancer patients by targeting BRCA1/2 expression." (PMID 36984544, 2023). "For patients with BRCA1/2-mutated ovarian cancer with secondary platinum-sensitive recurrence, the therapeutic effect of PARPi monotherapy and platinum-based chemotherapy was similar." (PMID 37891662, 2023). "Females harbouring BRCA1/2 pathogenic variants are at increased risk of developing breast/ovarian cancer." (PMID 37951914, 2023). "The results suggest that BRCA1 promoter methylation can have a potential role in ovarian cancer susceptibility, but larger more in-depth studies are required." (PMID 37434214, 2023). "This approach can be helpful in determining the functional impact of genetic variations in the BRCA1 gene, which is associated with an increased risk of BC and ovarian cancer." (PMID 38149678, 2023). "BRIP1 is instead included on the corresponding gene panel for ovarian cancer predisposition, together with BRCA1, BRCA2, PALB2, RAD51C, RAD51D and the Lynch syndrome genes." (PMID 37563628, 2023). "The authors suggested that BABAM1 was acting as the causal gene to modify breast and ovarian cancer risk based upon its physical interaction with the BRCA1 protein complex and its expression in ovarian cancer." (PMID 36859531, 2023). "Poly (ADP-ribose) polymerase inhibitors (PARPi) are selectively active in ovarian cancer (OC) with homologous recombination (HR) deficiency (HRD) caused by mutations in BRCA1/2 and other DNA repair pathway members." (PMID 37973845, 2023). "Our study revealed that ZNF251, a transcription factor, is a novel gene whose haploinsufficiency confers PARPi resistance in multiple breast and ovarian cancer lines harboring BRCA1 mutations." (PMID 37066268, 2023). "The ARIEL 2 study evaluated the effectiveness of rucaparib in recurrent, platinum-sensitive, high-grade ovarian carcinoma with either BRCA1 and BRCA2 (BRCA) mutations or genomic loss of heterozygosity (LOH) scores." (PMID 37190285, 2023). "Ovarian cancer has been associated with penetrant germline pathogenic mutations in tumor suppressor genes, especially BRCA1 and BRCA2." (PMID 37958970, 2023). "Targeted screening for high-risk groups: It is essential to design strategies that effectively target high-risk populations, such as individuals with a family history of ovarian cancer or known genetic predispositions, such as BRCA1 and BRCA2 mutations." (PMID 38084173, 2023). "In contrast, in another model of BRCA1-deficient ovarian cancer, PARP inhibition induced a therapeutic effect through STING activation, showing synergic effects with PD-1 blockade on antitumor T-cell response and survival." (PMID 36831435, 2023). "In ovarian cancer, 69.6% (78 of 112) of BRCA1/2 germline-variant tumors had 2-hit events, 94.9% (74 of 78) of which were via loss of heterozygosity (LOH)." (PMID 37523182, 2023).
ovarian carcinoma (continued). "The aim of this study was to evaluate the association of BRCA1 promoter methylation detected in blood-derived DNA with the risk of ovarian cancer." (PMID 37434214, 2023). "The lifetime risk of developing ovarian cancer is 40–45% for women with mutations in BRCA1 and 15–20% harboring BRCA2 mutations." (PMID 36305848, 2023). "Approximately 18% of ovarian cancer is associated with germline mutations, most attributed to BRCA1/2 mutations." (PMID 37370804, 2023). "Evidence suggests that BRCA1 mutation is linked to chemosensitivity and a better prognosis in patients with ovarian cancer." (PMID 37108451, 2023). "Women with BRCA1/2 PV have a lifetime risk of developing BC and ovarian cancer of 45% to 75% and 18% to 40%, respectively." (PMID 38067403, 2023). "The three main genetic risk factors include a family history of breast or ovarian cancer, BRCA1 and BRCA2 mutations, and lynch syndrome." (PMID 36376606, 2023). "In a murine model of BRCA1-deficient ovarian cancer, the use of olaparib to inhibit PARP1 promotes antitumor immunity, especially when it is combined with PD-L1-blocking antibodies, and this action is STING-dependent in mice with tumor xenografts." (PMID 38139802, 2023). "Overall, the results of the ARIEL4 study support the use of rucaparib as a viable alternative to chemotherapy for patients with relapsed, BRCA1/2-mutated ovarian carcinoma." (PMID 37035242, 2023). "In NOP, 86% of BRCA1 pathogenic germline variants were found in breast or ovarian cancer, including peritoneal cancer." (PMID 37916805, 2023). "Ultimately, our goal is to develop a highly specific test that can detect HGSOC, the deadliest form of ovarian cancer, at its earlier stages, especially in women who are at increased risk of developing ovarian cancer (e.g., BRCA1 and BRCA2 mutation carriers)." (PMID 37205573, 2023). "In vitro, the combined olaparib and PSPC1 small interfering RNA (siRNA) exhibited synergistic anti-proliferative activity in BRCA1/2-mutated breast and ovarian cancer cells." (PMID 38069409, 2023). "The chance of developing breast and ovarian cancers is considerably increased by inheriting a deleterious mutation in either the BRCA1 or BRCA2 gene." (PMID 37886170, 2023). "In this analysis, the GIS distribution of BRCA1/2-deficient ovarian cancer samples was used as a comparator to evaluate GIS distributions in BRCA1/2-deficient ER + BC and TNBC samples." (PMID 37589839, 2023). "We multiply ascertained the BRCA1 pathogenic missense variant c.5207T > C; p.Val1736Ala (V1736A) in clinical investigation of breast and ovarian cancer families from Orkney in the Northern Isles of Scotland, UK." (PMID 36927983, 2023). "One study including 107 patients diagnosed with breast or ovarian cancer revealed that the c.5266dupC Ashkenazi founder mutation was the most common BRCA1 pathogenic variant reported in 36.67% of cases, closely followed by c.3607C>T in 30% of cases." (PMID 37239058, 2023). "The risk for ovarian cancer in female relatives of BRCA1 carriers is even higher than female relatives of BRCA2 carriers." (PMID 36861435, 2023). "If breast and ovarian cancer are diagnosed in the family, the probability of carrying germline mutations of BRCA1 or 2 is 60%." (PMID 36837501, 2023). "Using the triangulation tool she looks to be an ancestor on my mother’s side...My query to you is what are the possible reasons that this woman matched me on the mutated section of my BRCA1 gene and has had ovarian cancer, yet doesn’t seem to have my variant." (PMID 37079361, 2023). "The increased risks of breast and ovarian cancer are linked to pathogenic variations (PVs) in BRCA1 and BRCA2." (PMID 37804357, 2023). "The prevalence of BRCA1/2 mutations is highest in ovarian cancer (21%) and around 5% in several other cancers, including breast, prostate, pancreatic, non-small cell lung, bladder, and bile duct cancers." (PMID 38069409, 2023).